MC1R (melanocortin 1 receptor)
Diseases named in the same sentence as MC1R in open-access papers (continued):
Sharing a sentence is not in itself a finding about the gene and the disease.
tumor (continued). "Approximately 95% of tumor uptake of 67Cu-NOTA-GGNle-CycMSHhex was decreased by 10 μg (6.07 nmol) of NDP-MSH blockade (p < 0.05), indicating that the tumor uptake was MC1R-specific." (PMID 37345092, 2023). "On day 24, six of the seven (85.7%) mice that received the WT T-47d cells had tumors, while only one of the mice that received the MC1R-KD T-47d cells had a tumor, suggesting that MC1R signaling was critical for imparting tumorigenicity in T-47d cells." (PMID 37679505, 2023). "In wild-type mice, MC1R depletion slowed tumor growth and enhanced the efficacy of anti-PD-1 treatment." (PMID 37714844, 2023). "In wild-type mice, MC1R depletion slowed B16F10-dCas9 tumor growth, leading to a significant survival advantage for tumor-bearing mice." (PMID 37714844, 2023). "Approximately 94% of tumor uptake of 67Cu-NOTA-PEG2Nle-CycMSHhex was blocked by 10 μg (6.07 nmol) of NDP-MSH (p < 0.05), suggesting that the tumor uptake was MC1R-mediated." (PMID 37345092, 2023). "This was motivated by our previous work on the development of MC1R-targeting radiopharmaceuticals, which showed that a piperidine-based linker was essential in increasing the tumor-to-kidney ratios." (PMID 35890397, 2022). "In contrast, the levels of ENO2, GABBR1, and MC1R were significantly elevated in tumor tissues compared with normal tissues." (PMID 35872794, 2022). "Among these genes, PLK1, CDC25C, ESCO2, AXIN2, TREX2, ALKBH2, and MC1R were upregulated in tumor tissues, whereas IGF1 and ESR1 presented downregulation." (PMID 35484177, 2022). "Studies have found that MC1R promotes several tumor behaviors, including cell proliferation and differentiation, pigment formation, and genome damage repair." (PMID 34698109, 2021). "In this study, we demonstrated a cooperative anti-tumor effect arising from the combination of ICIs and systemic targeted α-particle radiotherapy using 212Pb labeled MC1R-targeted peptide [212Pb]VMT01." (PMID 34359580, 2021). "Further analysis indicated that differential methylation of the CpG island in tumours mainly affected the expression of MC1R, and less so of TUBB3." (PMID 33248005, 2021). "We explored the expression of MC1R in clinical samples and found that MC1R expression was lower in CRC tumor tissues than in normal tissues at both the mRNA and protein levels." (PMID 34698109, 2021). "Forty-seven (77.0%) and forty-four (72.1%) cases showed that MC1R was expressed at lower levels in CRC tumor samples than in normal tissue by RT-qPCR and Western blotting, respectively." (PMID 34698109, 2021). "The results showed a significant decrease (p < 0.0001) in the mRNA level of MC1R in CRC tumor samples in comparison to normal samples." (PMID 34698109, 2021). "Further studies are needed demonstrate the efficacy of combination of [212Pb]VMT01 and ICIs in preclinical models with multiple tumor sites that displays heterogeneous expression of MC1R." (PMID 34359580, 2021). "A detrimental effect of higher peptide dose had also been described in the first study describing DOTA-NAPamide as an MC1R tracer: tumor uptake at 170 pmol or 420 pmol peptide was much lower than with just 20 pmol." (PMID 31163066, 2019). "These experiments would also tell us if secreted ASIP retained inverse agonist activity against MC1R-driven melanogenesis on neighboring ASIP-null tumor cells." (PMID 27028866, 2016). "We also observed statistically significant differences between sun-sensitive and sun-resistant individuals with respect to associations between MC1R genotype and AJCC prognostic tumor characteristics." (PMID 25790105, 2015). "Few studies have reported on MC1R variation with respect to tumor characteristics, especially clinically important prognostic features." (PMID 25790105, 2015). "A more rigorous model will be needed to confirm that Mc1r can affect exit from the primary tumor, the first step of metastasis." (PMID 22363655, 2012).
tumor (continued). "Inherited MC1R variants modulate MITF transcription factor signaling, which in turn affects tumor cell proliferation, apoptosis, and DNA repair." (PMID 22325793, 2012). "Importantly, deletion of MC1R accelerates tumor growth of HCC, which is reversed by the treatment of YAP-TEAD complex inhibitor verteporfin." (PMID 40473594, 2025). "It would, however, be informative to study if MC1R status correlates with expression of PD‐L1 or other immune checkpoints in the tumor microenvironment that could affect the tumor immunogenicity." (PMID 40926353, 2025). "In line with the suppressive role of MC1R signaling in tumor growth, we initiated the hypothesis that vitamin C might enhance the anticancer effect of α-MSH." (PMID 40473594, 2025). "Moreover, we transplanted B16F10-dCas9 cells into the Cas9 transgenic mice and observed that Mc1r depletion slowed B16F10-dCas9 tumor growth." (PMID 37714844, 2023). "In contrast, deleting Mc1r from parental B16F10-Cas9 significantly slowed tumor growth." (PMID 37714844, 2023). "This suggests a pigmentation-independent effect of MC1R on the tumor number." (PMID 36765822, 2023). "To examine whether MC1R promotes immune evasion of HCmel1274, we transplanted HCmel1274-dCas9 cells transduced with NTC or Mc1r sgRNA into mice and monitored tumor growth." (PMID 37714844, 2023). "To confirm the tumorigenic effect of MC1R, we xenografted WT or MC1R-KD T-47d cells subcutaneously into the hind flanks of athymic nude mice carrying a subcutaneous 17β-estradiol pellet on the back of their necks to support tumor formation." (PMID 37679505, 2023). "However, in one notable example, the melanocortin-1 receptor (MC1R) requires palmitoylation by DHHC13 to enable its tumor-suppressor function in melanocytes." (PMID 35624824, 2022). "Palmitoylation of MC1R at Cys315 is required for MC1R tumor suppressor function." (PMID 34803494, 2021). "Surprisingly, this result was substantially consistent with the analysis of clinical CRC tumor samples, and both analyses indicated that high MC1R expression was more likely correlated with MMR genes, which further suggested that high MC1R expression was significantly associated with MSI." (PMID 34698109, 2021). "In cell uptake studies in the same cell line, the uptake of [99mTc]Tc-43 could not be blocked using monospecific RGD but only by addition of NDP-MSH, indicating the tumor cell uptake to be solely mediated by the MC1R." (PMID 32751666, 2020). "Thus, 4-arm DOTA peptides will be effective for tumor diagnosis because of their slightly higher lipophilicity, higher MC1-R affinity, and relatively higher stability compared to 3-arm DOTA peptides." (PMID 30901323, 2019). "Compounds such as [111In]DOTA-NAP-amide exhibit high affinity for the MC1R in vitro, good tumor uptake in vivo, but they may suffer from relatively high kidney uptake and retention in vivo." (PMID 28491052, 2017). "For example, ASIP may influence survival and in vivo tumor growth by inhibition of MC1R found on the tumor vasculature." (PMID 27028866, 2016). "Since α-MSH via binding to MC-1R up-regulated cytotoxicity in tumor-specific CD8+ T cells we speculated that C57BL/6Je/e mice might exhibit impaired anti-tumoral immunity." (PMID 20126537, 2010). "There were no data concerning whether MC1R polymorphisms could be used as a tumor prognosis factor to predict the survival of CRC patients." (PMID 34698109, 2021). "While the presence of MC1R variation has not been associated with histopathologic characteristics, it was found to correlate with tumor presentation on the arms, which may provide additional support for its UV-risk independence." (PMID 32429485, 2020). "More specific signs are hypotension and skin hyperpigmentation; the latter is generally more prominent on mucosae and on sun-exposed areas or over pressure points such as elbows and knees, and result from enhanced activation of skin melanocortin 1 receptors [MC1R]." (PMID 30728045, 2019).
tumor (continued). "Additionally, the presented data indicate that alpha-melanocyte-stimulating hormone via signaling through a functional melanocortin-1 receptor augmented antitumoral immunity by up-regulating the expression of cytotoxic genes and enhancing the cytolytic activity in tumor-specific CD8+ T cells." (PMID 20126537, 2010). "Importantly, injection of tumor-antigen specific CD8+ T cells stimulated via α-MSH/MC-1R signaling into tumor-bearing recipient mice significantly reduced progressive tumor growth indicating that α-MSH/MC-1R interactions were crucial for the induction of tumor-specific cytotoxic T lymphocytes." (PMID 20126537, 2010). "MC1R further triggers phosphorylation and inactivation of YAP via cAMP-PKA signaling to restrain tumor growth." (PMID 40473594, 2025). "To further valid the suppressive function of MC1R in vivo, we carried out xenograft model by subcutaneously injecting sgMC1R HCC cells into athymic nude mice and monitored the tumor growth." (PMID 40473594, 2025). "Since MC1R functions as a tumor suppressor in HCC, we attempted to propose a novel strategy for HCC therapy via activation of MC1R signaling." (PMID 40473594, 2025). "We then transplanted MC1R-depleted B16F10-dCas9 cells expressing wild-type GNAS or the R201C mutant into mice and monitored tumor growth over time." (PMID 37714844, 2023). "Genetic analysis reveals that MC1R signals through the GNAS-PKA axis to repress the transcription of chemokine genes CXCL9/10/11, resulting in impaired T cell infiltration into the tumor microenvironment." (PMID 37714844, 2023). "By activating the GNAS-PKA axis, MC1R inhibits interferon-gamma induced CXCL9/10/11 transcription, thus impairing T cell infiltration into the tumor microenvironment." (PMID 37714844, 2023). "Several of the genes described here can be assigned to categories that are involved in the development of solid tumors: MC1R is involved in pigmentation/UV protection, EPB41 and MYCT in tumor suppression, and ADGRG3 in immunomodulation." (PMID 37444464, 2023). "In comparison to two control sgRNAs targeting nonessential genes Rosa26 and H11, two independent sgRNAs targeting Mc1r blocked α-MSH-induced CREB1/ATF1 phosphorylation and slowed tumor growth." (PMID 37714844, 2023). "MC1R also interacts with the signal transducer GNAS, recently suggested to be tumor-promoting in RCC." (PMID 34067022, 2021). "In this part, we examine the expression of MC1R at the protein and mRNA levels in 86 CRC tumor tissues and 83 adjacent normal tissues by RT-PCR and Western blotting, respectively." (PMID 34698109, 2021). "Although the two approaches had different truncation points, their tendency of MC1R expression was the same, and both indicated that MC1R was expressed at lower levels in CRC tumor samples than in normal samples." (PMID 34698109, 2021). "Since melanocytes expressed MC1R and POMC—which can affect also endogenously MC1R and other MC receptors—rational combination of targeting peptides of MSH and POMC peptides can provide much higher inhibition of the tumor." (PMID 38256168, 2024). "In contrast, MC1R depletion did not affect tumor growth in immunodeficient TCRβ or RAG1 knockout mice." (PMID 37714844, 2023). "In contrast, MC1R depletion did not affect tumor growth or host survival in immunodeficient NOD-Prkdc-Il2r gamma (NCG) mice or T cell receptor beta (TCRβ) knockout mice." (PMID 37714844, 2023). "Deleting Mc1r (by expressing the Mc1r sgRNA) from these two clones did not result in statistically significant difference in tumor growth or animal survival relative to control." (PMID 37714844, 2023). "Three genes (RARS, MC1R, and RGS3) were involved in tumor metastasis other than CRC." (PMID 35795065, 2022). "The data for MC1R expression were analyzed with Student’s t test, and the results showed that both the expression of MC1R at the protein and mRNA levels were significantly lower in CRC tumor samples (N = 61) than in paired normal tissues (p < 0.05)." (PMID 34698109, 2021).
tumor (continued). "Although there is no clear evidence to support an effect of somatic tumor variation by MC1R status, it is difficult to exclude the possibility." (PMID 22325793, 2012). "Consequently, lack of MC1R boosts tumor growth, which can be dramatically repressed by verteporfin treatment." (PMID 40473594, 2025). "However, not all lesions express the MC1R, resulting in an incomplete visualization of the tumor load and thus false staging of the disease." (PMID 34200477, 2021). "111In-labeled 4-arm DOTA-α-MSH yields higher tumor accumulation and lower renal accumulation than 111In-labeled 3-arm DOTA-α-MSH because the chemical properties of the 4-arm DOTA construct include slightly higher lipophilicity, significantly higher MC1-R affinity, and relatively higher stability." (PMID 30901323, 2019). "Moreover, a melanocortin 1 receptor-targeting peptide conjugate, DOTA-modified cyclized α-melanocyte-stimulating hormone (DOTA-CycMSH), was radiolabeled with 225Ac and proof-of-principle biodistribution studies using B16F10 tumour-bearing mice were conducted." (PMID 31659557, 2019).
cancer (41 papers, 2002 to 2025). A tumor composed of atypical neoplastic, often pleomorphic cells that invade other tissues. "To study the effect of the disruptive MC1R variants on different cancer types, we extracted MC1R DNA germline variants from the whole-exome sequences of 10,391 patients with cancer housed in TCGA." (PMID 37679505, 2023). "Herein, we demonstrate that disruptive MC1R variants associated with melanomagenesis are less frequently found in patients with several cancers." (PMID 37679505, 2023). "MC1R is a highly polymorphic gene—most polymorphisms are caused by SNPs—and is associated with skin phenotypes and increased cancer risk." (PMID 34698109, 2021). "Polymorphisms of the melanocortin 1 receptor (MC1R) gene, in particular, correlate with fairness of skin, UV sensitivity, and enhanced cancer risk." (PMID 23749111, 2013). "Genetic factors may influence the risk of UV-mediated skin diseases, e.g. polymorphisms of the melanocortin 1 receptor (MC1R) gene confer increased susceptibility to cancer risk." (PMID 38846010, 2024). "However, surprisingly, our preliminary analysis revealed a significant association between active MC1R germline variants and the development of different cancers." (PMID 37679505, 2023). "However, the physiological effect of the MC1R variants in promoting cell growth and cancer progression should be further evaluated in other models." (PMID 37679505, 2023). "Common genetic mechanisms, especially those underlying cell cycle turnover and protein regulation such as those involving SNCA, PARK2, PARK8, ATM, PTEN, PINK1, and MC1R have been implicated in both neurodegeneration and cancer and perhaps explain this association." (PMID 32547471, 2020). "Thus, the members of these branches received negative test results for the familial LS-causing pathogenic variants but some members nevertheless had elevated cancer risks due to the finding of one or both MC1R and NBN variants, for which they were appropriately counseled." (PMID 36612224, 2022). "Since MC1R signaling is potentially targetable by agents that influence cAMP levels, pharmacologic manipulation of cutaneous cAMP may be a useful approach to reduce UV sensitivity and cancer risk." (PMID 23749111, 2013). "New insights into the ways in which MC1R and other genes function to protect the skin against the harmful consequences of UV may allow the rational development of pharmacologic strategies to reduce UV sensitivity and cancer risk." (PMID 23749111, 2013). "First, we conducted a haplotype analysis adjusted for sex and family history of cancer for the variants of the OCA2 and HERC2 genes and a separate analysis for the variants of the MC1R gene." (PMID 40429816, 2025). "For instance, mutations in genes such as SNCA (α-synuclein), ATM (ataxia telangiectasia mutated), PARK2 (parkin), PARK8 (LRRK2), MC1R (Melanocortin 1 receptor) and PTEN (Phosphatase and tensin homolog) have been identified in both PD and certain cancers." (PMID 39563740, 2024). "SSTR2-SST is also one of the axes with the strongest literature support for a role in cancer, along with several others, including MC1R-POMC and GHRHR-GHRH." (PMID 38723607, 2024). "Our results show widespread expression of MC1R across different tissues and, importantly, in different cancers." (PMID 37679505, 2023). "We explored the relevance of MC1R in human cancers by examining the expression profiles of MC1R in 33 human cancer types versus normal tissues using TCGA and the Genotype-Tissue Expression (GTEX) RNA-seq datasets." (PMID 37714844, 2023). "Similar to findings in vitro, significantly higher levels of Cxcl9/10/11 were observed in cancer cells isolated from MC1R-depleted tumors relative to control tumors." (PMID 37714844, 2023). "This has been found, for example, for modular nanotransporters for delivering cytotoxic agents into the nuclei of cancer cells with the overexpression of the EGFR or the melanocortin 1 receptor." (PMID 36986848, 2023).